RBM47 (RNA binding motif protein 47)
Diseases named in the same sentence as RBM47 in open-access papers (continued):
Sharing a sentence is not in itself a finding about the gene and the disease.
Kidney Clear Cell Carcinoma (1 paper, 2023). "Here, we demonstrated the expression and the prognostic role of RBM47 in public databases and clinical samples of clear cell renal carcinoma (ccRCC) with bioinformatics analysis." (PMID 37962768, 2023).
lung injury (1 paper, 2023). "Further investigations revealed that deficiency of RBM47-ISGylation (K329R KI) leads to multifaceted immunosuppression by inducing TSC22D3 expression, which impairs tissue homeostasis, leading to acute lung injury (ALI) and lung tumorigenesis." (PMID 38036512, 2023).
lymphoma (1 paper, 2022). A malignant (clonal) proliferation of B- lymphocytes or T- lymphocytes which involves the lymph nodes, bone marrow and/or extranodal sites. "On the other hand, in samples below PLA2G2A and RBM47, the expression cut-off, the expression of AQP1 (calculated cut-off: 30 counts, p = 0.026) divided them into the two separate subgroups comprising lymphomas and mild NSOI, respectively." (PMID 35955742, 2022).
metastatic cancer (1 paper, 2014). A carcinoma which has spread from the original site of growth to another anatomic site. "Taken together, these observations suggested that RBM47-dependent suppression of tumor progression was partially mediated by its ability to increase the production of the Wnt antagonist DKK1, a secreted protein that can inhibit tumor phenotypes in metastatic cancer cells." (PMID 24898756, 2014).
neuroblastoma (1 paper, 2020). Neuroblastoma (NB) is the most common solid, extracranial childhood tumor. "For example, in the large SEQC cohort, RBM11, RBM20, RBMX2 were all upregulated in stage 4 neuroblastoma, compared to 4S with RBM47 being downregulated." (PMID 32707690, 2020).
Obesity (1 paper, 2025). Accumulation of substantial excess body fat. "However, four of the 24 common microglial DEGs were regulated in opposite directions by obesity in males and females (Unc13a, Atp1a3, and Arhgap33 upregulated in females and downregulated in males; Rbm47 upregulated in males and downregulated in females)." (PMID 41310161, 2025).
oligoasthenoteratozoospermia (1 paper, 2021). A form of male infertility that is characterized by a combination of low number or oligozoospermia, poor motility or asthenozoospermia, and abnormal shape or teratozoospermia of sperms. "In our study, the homozygous allele (T–T) of the RBM47 gene induced oligoasthenoteratozoospermia, whereas the allele (T–T) determined high levels of all sperm traits." (PMID 34178030, 2021).
osteosarcoma (1 paper, 2023). A usually aggressive malignant bone-forming mesenchymal neoplasm, predominantly affecting adolescents and young adults. "The RBM47 and IGF2BP1 mediated circular FNDC3B/FNDC3B mRNA imbalance was involved in the malignant processes of osteosarcoma in vitro and in vivo." (PMID 38129874, 2023).
polyp (1 paper, 2023). A usually exophytic mass attached to the underlying tissue by a broad base or a thin stalk. "By contrast, colonic polyp count was reduced in Rbm47-IKOApcMin/+ mice, with no change in polyp size." (PMID 37014710, 2023).
staphylococcus aureus infection (1 paper, 2025). An infectious process in which the bacteria Staphylococcus aureus is present. "The signaling pathways most significantly associated with RBM47 were those implicated in the host immune responses against tuberculosis and Staphylococcus aureus infections." (PMID 39757245, 2025).
ulcerative colitis (1 paper, 2019). An inflammatory bowel disease involving the mucosal surface of the large intestine and rectum. "In addition, we demonstrated that the overexpression of Rbm47 enabled B cells to facilitate Foxp3+ regulator T-cell induction and reduce the severity of DSS-induced ulcerative colitis." (PMID 29844590, 2019).
Wilms tumor (1 paper, 2024). An embryonal neoplasm characterized by the presence of epithelial, mesenchymal, and blastema components. "The identified prognostic genes, particularly GRAMD1A, SPR, EBAG9, RBM47, and RIDA, offer significant potential as both prognostic biomarkers and therapeutic targets for improving personalized treatment in Wilms tumor patients." (PMID 39659787, 2024).
tumor (39 papers, 2014 to 2026). "Mice with intestinal Rbm47 deficiency had abnormally shaped villi in the small intestine and spontaneously developed intestinal and colonic polyps, implying a tumor-suppressive role of Rbm47 in the intestine." (PMID 41335176, 2025). "Following that, RBM47 was selected for further study according to the association between gene expression and tumor immunity." (PMID 39741300, 2024). "We also found that low RBM47 expression was positively associated with bigger tumor size and higher TNM stage of PTC patients." (PMID 35338124, 2022). "Some of the identified prognostic DE RBPs have been reported associated with tumor progression, such as RBM47, LUZP4, AFF3, PPARGC1A, PPARGC1B, PABPC3, and PNLDC1." (PMID 33224957, 2020). "Taken together, these results demonstrate that down-regulation RBM47 is highly associated with tumor progression and EMT." (PMID 28680090, 2017). "We also showed that elevated expression of RBM47 is strongly associated with the epithelial cell state in multiple cancer types, whereas its expression is strongly decreased in mesenchymal-like tumor cells." (PMID 28680090, 2017). "We propose that RBM47 can broadly alter the splicing pattern of these genes and modifies the expression level, amino acid sequences or structures of the encoded proteins, and finally changes their functions in tumor cells." (PMID 40695891, 2025). "In fact, RBM47-dependent basal B-specific splicing events were found to be functionally interconnected by physical and/or genetic interactions, which points to the existence of a common basal B-specific regulatory network associated with tumour malignancy." (PMID 33845831, 2021). "However, it is interesting to note that mutations of RBM47, are linked with carcinogenesis, and it is a potential tumor suppressor gene." (PMID 30591678, 2018). "With comparable effects of RBM47 re-expression seen in both the lung and brain metastasis models, we chose the lung colonization assay for loss-of-function studies as this allowed the simultaneous analysis of a greater number of tumor re-initiation events." (PMID 24898756, 2014). "This could reflect either weak tumor suppressive function of RBM47 in general, heterogeneity in the sensitivity to RBM47 among different cancer cell subpopulations, or in the case of RBM47 reintroduction, loss of transgene expression." (PMID 24898756, 2014). "In order to identify up-stream regulators and oncogenic signaling pathways that may cause the observed down-regulation of RBM47 in mesenchymal-like cancer cells during tumor progression, we analyzed RBM47 expression after experimental induction of EMT in CRC cell lines." (PMID 28680090, 2017). "Our further experimentation strongly supports RBM47 as a central mediator of LINC00862's tumor-suppressive effects." (PMID 41487470, 2026). "RBM47 appears to promote an immunosuppressive tumor microenvironment through M2 macrophage enrichment and its association with inhibitory immune checkpoints." (PMID 39757245, 2025). "While this manuscript focuses on the regulation and upstream factors of RBM47, future studies should identify pathways and targets downstream of RBM47 that mediate tumor suppression by the FOXA1/RBM47 axes." (PMID 41335176, 2025). "In summary, our results demonstrated the anti-tumor function and the globally downstream targets of RBM47 in CRC cells." (PMID 40695891, 2025). "Functional enrichment analysis revealed that these DEGs and RASEs were primarily enriched in biological processes such as cell cycle, apoptosis, and DNA repair, which are closely related to the tumor-suppressive role of RBM47." (PMID 40695891, 2025). "Members of the RBM family such as RBM3 and RBM47 display context-specific roles, acting as tumor suppressors in some settings and as oncogenic enhancers of Wnt in others." (PMID 41516083, 2025).
tumor (continued). "By searching the literature, we found that the RBM38’s role in the development of PC has been reported, and RBM47 and RBMS3 were closely associated with tumor immunity." (PMID 39741300, 2024). "In the subcutaneous tumor model, the attenuated tumor growth resulting from LOC101927668 knockdown was partially restored upon depletion of RBM47." (PMID 39350250, 2024). "A previous research also evidenced that RBM47 knockout mice exhibited less tumor formation after undergoing AOM/DSS treatment." (PMID 39741300, 2024). "In the current study, we found the higher RBM47 expression in PC tumor tissues by dataset analysis and explored the effects of RBM47 on PC progression." (PMID 39741300, 2024). "Representative images of immunofluorescence staining and quantitative analysis showed that RBM47 overexpression increased the percentage of Ki67-postive cells and its knockdown exhibited the opposite effect in tumor tissues of nude mice." (PMID 39741300, 2024). "RBM47 overexpression drove PC progression by promoting cell proliferation and xenografted tumor growth." (PMID 39741300, 2024). "Generally, our research revealed the direct role of RBM47 in suppressing CC and modulating CXCL13 within TLS, emphasizing the significance of RBM47 in promoting anti-tumor immune responses and impeding tumor advancement." (PMID 38914961, 2024). "Conversely, xenotransplantation of RBM47-knockdown PC cells led to smaller tumor bodies in mice from the 15th day." (PMID 39741300, 2024). "Confocal microscopy images and quantitative analysis of fluorescence intensity showed that RBM47 overexpression promoted F-actin accumulation at the contact between NK cells and tumor cells." (PMID 39741300, 2024). "By subsequent in vitro and in vivo experiments, we found that RBM47 promotes malignancies of PC cells, including cell proliferation and xenografted tumor growth." (PMID 39741300, 2024). "As a novel and evolutionarily conserved RNA-binding protein (RBP) in vertebrates, RBM47 is increasingly recognized for its role as a tumor regulator." (PMID 39659787, 2024). "The effect of RBM47 stably knockdown on LOVO cells with depleted LOC101927668 was also investigated using an orthotopic liver xenograft tumor model." (PMID 39350250, 2024). "RBM47 knockdown corresponded to the upregulated respiratory metabolism and drug resistance of lung adenocarcinoma A549 cells and promoted xenografted tumor growth in nude mice." (PMID 39741300, 2024). "The overexpression or knockdown efficiency of LOC101927668 was confirmed in tumor samples from mouse xenograft models through RT-qPCR, accompanied by corresponding changes in RBM47 expression by Western blot analyses." (PMID 39350250, 2024). "Functioning as a multifaceted RBP, RBM47 is involved in diverse biological and pathological processes, including early embryonic development, C to U RNA editing, and tumor suppression." (PMID 39350250, 2024). "In conclusion, previous studies showed that RBM47 had the certain clinical implications in various tumors and participated in tumor formation." (PMID 37962768, 2023). "Here, in OS, we for the first time demonstrated that RBM47 was downregulated and acted as a tumor suppressor gene to restrain cancer progression in vitro and in vivo." (PMID 38129874, 2023). "The results showed that RBM47 overexpression significantly reduced the tumor volume and tumor weight." (PMID 37660095, 2023).
tumor (continued). "Further analysis of The Cancer Genome Atlas (TCGA) database revealed a stepwise reduction of RBM47 expression with advancing tumor stage, which was independently predictive of both overall and progression-free survival." (PMID 37014710, 2023). "At the same time, RBM47 also partially applies its tumor-suppressive functions through modulating mRNA stability by 3’UTR binding." (PMID 35831298, 2022). "Here, in HCC, we identified that RBM47 had an inhibitory influence on tumor behaviors in vitro and accordingly suppressed the growth and metastasis of xenograft tumors in vivo." (PMID 35831298, 2022). "The RBM47 (RNA Binding Motif Protein 47) gene is an RNA-binding protein that controls cell fate decisions and has been suggested to be a tumor suppressor." (PMID 35629146, 2022). "In cancers, the aberrant expression of RBM47 influences the transcriptional or posttranscriptional regulation of multiple tumor-suppressor and proto-oncogenic targets across diverse cancer types." (PMID 35831298, 2022). "Taken together, we concluded that RBM47 functioned as a tumor suppressor by upregulating UPF1, acting as a DNA/RNA binding protein at the transcriptional and posttranscriptional levels." (PMID 35831298, 2022). "Consistent with previous investigations, RBM47 had a tumor-suppressive function in HCC via 3’UTR binding." (PMID 35831298, 2022). "RBM47 has been considered as a tumor suppressor as it suppressed the progression of breast cancer, colon cancer, and lung cancer." (PMID 35338124, 2022). "Recently, RNA-binding motif protein 47 (RBM47) has been suggested to function as a tumor regulator by acting as an RNA binding protein (RBP), but its role in HCC remains ambiguous." (PMID 35831298, 2022). "In contrast, as RBM47 expression, which was higher in females than in males, increased, tumor grade, AJCC stage, and T stage in KIRC patients decreased." (PMID 33229623, 2020). "In our study, we found mutations in the RNA binding domains of RBM47 and RPL5, which are suggested to be tumor suppressors in a few cancers." (PMID 28035070, 2017). "In line with this, both the up- and down-regulated target genes of RBM47, as well as the genes that were targets of RBM47-mediated alternative splicing, contain genes that have previously been shown to either promote or inhibit tumor phenotypes." (PMID 24898756, 2014). "For example, DKK1, HTATIP2, HBP1, MXI1 and CASP7, all bound by RBM47 and upregulated upon RBM47 reintroduction, have known tumor suppressive functions." (PMID 24898756, 2014). "One of the most highly bound RBM47 mRNA targets, the secreted Wnt inhibitor DKK1, is stabilized by RBM47 and partially mediates RBM47 tumor suppressive function." (PMID 24898756, 2014). "Therefore, our results establish GSDMA as a critical downstream mediator of RBM47-induced tumor suppression that links epithelial differentiation and pyroptosis to chemotherapy sensitivity." (PMID 41681975, 2026). "We extend the cellular and molecular cognition of RBM47 in tumor." (PMID 40695891, 2025). "RBM47 acts tumor suppressive in breast, lung and CRC cell lines and mouse models." (PMID 41335176, 2025). "Finally, the AS results were consistent with our RT-qPCR detection results, further confirming the anti-tumor function of RBM47 in CRC." (PMID 40695891, 2025). "It is hypothesized that the dual nature of RBM47’s impact on tumorigenesis may be influenced by factors such as tumor heterogeneity, pathological subtypes, or molecular mechanisms, leading to disease-specific outcomes." (PMID 38914961, 2024). "Consistent with the findings in subcutaneous tumors, the attenuation of tumor metastasis due to downregulated LOC101927668 expression could be partially reversed by decreased RBM47 expression." (PMID 39350250, 2024).
tumor (continued). "Recent studies suggest that RBM47 acts as a tumor suppressor by stabilizing tumor suppressor mRNAs." (PMID 38036512, 2023). "Furthermore, the protein levels of RBM47 were decreased in ccRCC cancer tissues in public database (the Clinical Proteomic Tumor Analysis Consortium, CPTAC) and clinical samples with immunohistochemistry." (PMID 37962768, 2023). "Also, the expression of RBM47 was negatively correlated with the tumor grade of RCC according to the TCGA-KIRC database." (PMID 37660095, 2023). "Mechanistically, RBM47 might play a tumor suppressive role by regulating the stability of e-cadherin RNA in the EMT signaling pathway in ccRCC." (PMID 37962768, 2023). "It is widely accepted that RBM47 functions as a tumor suppressor in multiple cancers." (PMID 37981573, 2023). "Taken together, IDH1-AS1 may suppress EOC cell proliferation and tumor growth via the miR-518c-5p/RBM47 axis." (PMID 37981573, 2023). "The experimental results indicated that overexpression of RBM47 could inhibit tumor cell invasion and migration ability." (PMID 37962768, 2023). "In current study, we determined that RBM47 could exert tumor suppressive effects via UPF1 and we identified several DNA/RNA binding motifs by sequencing." (PMID 35831298, 2022). "RBM47 has also been recognized as a posttranscriptional regulator of epithelial cell-specific alternative splicing events and as a modulator of mRNA stability for key Wnt/β-catenin signaling antagonists, through which it exerts tumor-suppressive effects." (PMID 35831298, 2022). "Importantly, in the cell types analysed, ESRP1/2 and RBM47 induce the epithelial, basal A-like splicing phenotype, suggesting a potential tumour suppressor effect for these splicing regulators." (PMID 33845831, 2021). "In addition, expression of RBM47 correlates with a good prognosis in patients with lung, breast, and gastric cancer suggesting a tumor-suppressive role." (PMID 30591678, 2018). "Given its diverse functions, the tumor suppressive properties of RBM47 may be mediated by several different targets and/or mechanisms." (PMID 28680090, 2017). "Since both cytokines lead to repression of RBM47 in tumor cells, this might represent an important mechanism as to how the tumor microenvironment promotes cancer progression." (PMID 28680090, 2017). "Besides, RBM47 is a post-transcriptional regulator of RNA during tumor progression." (PMID 40066453, 2025). "Therefore, RBM47 is commonly regarded as a functional tumor suppressor in multiple cancer types." (PMID 35831298, 2022). "Therefore, RBM47 may have undiscovered roles as a multifunctional tumor suppressor in HCC." (PMID 41487470, 2026). "Our findings demonstrate that RBM47- and PTBP1-mediated alternative splicing of KRAS contributes to enhanced tumor progression, highlighting KRAS alternative splicing as a promising therapeutic target for cancer treatment." (PMID 41368203, 2026). "RBM47 has been found to bind to the 3′UTR of DKK1 mRNA and stabilize it, resulting in tumor suppression via Wnt inhibition in breast cancer." (PMID 41516083, 2025). "We discovered five tumor antigens (P2RY6, PLA2G2D, RBM47, SEL1L3, and SPIB) that are significantly increased and mutated, which correlate with the survival of patients and the presence of immune cells that present these antigens." (PMID 40066453, 2025). "Specifically, GRAMD1A was significantly overexpressed in tumor tissues, while RIDA, RBM47, and SPR showed higher expression levels in normal kidney tissues." (PMID 39659787, 2024). "Because previous studies have reported that RNA binding motif protein 47 (RBM47), zinc finger protein 621 (ZNF621), and cytosolic arginine sensor for mTORC1 subunit 2 (CASTOR2) function as tumor suppressors, we selected these genes for further verification." (PMID 37981573, 2023).